CPHL1P (ceruloplasmin and hephaestin like 1, pseudogene)
Synonyms: formerly CPHL1
Gene: Transcribed unitary pseudogene on chromosome 3 (149,229,431 to 149,276,664, reverse strand). Ensembl gene ENSG00000240216.
Diseases named in the same sentence as CPHL1P in open-access papers:
CPHL1P is named in the same sentence as 2 diseases in open-access papers, as found by Europe PMC text mining. Sharing a sentence is not in itself a finding about the gene and the disease. The quoted sentences say what the papers report.
clear cell renal cell carcinoma (1 paper, 2021). "Different from CMAHP, higher expression of unitary pseudogene CPHL1P was associated with worse patient OS (log-rank test, p = 4.98 × 10-6) in clear cell renal cell carcinoma (KIRC) and worse patient RFS (log-rank test, p = 0.00245) in prostate cancer (PRAD), respectively." (PMID 34425866, 2021).
CPHL1P also shares sentences with these, for which no sentence is quoted: prostate carcinoma (1 paper).